IRF1 (interferon regulatory factor 1)
Diseases named in the same sentence as IRF1 in open-access papers (continued):
Sharing a sentence is not in itself a finding about the gene and the disease.
melanoma (continued). "Taken together, the present results suggest that IL-27 exerts anti-proliferative activity against human melanomas by mechanisms similar to those of IFN-α in a STAT1/IRF-1–dependent manner and partly in a TRAIL-dependent manner." (PMID 24155891, 2013). "IRF-1 is essential for cytotoxic T cell and natural killer cell function in vivo and we previously observed that IRF-1 is consistently expressed together with several ISGs in melanoma metastases of patients receiving rIL-2." (PMID 16805915, 2006). "Indeed, high levels of nuclear IRF1 in melanoma cells correlate with better PFS in patients treated with anti-PD-1 therapy." (PMID 40108693, 2025). "IRF1 inhibited antitumor immunity by upregulating PD-L1 in colon adenocarcinoma and melanoma cells." (PMID 38789431, 2024). "Studies on melanoma cells have demonstrated that the PD-L1 gene might be regulated by IFN-γ produced by T-cells through the JAK/STAT/IRF1 (Interferon regulatory factor 1) pathway." (PMID 39343796, 2024). "Importantly, ATXN3 expression was increased in human lung adenocarcinoma and melanoma, and its levels were positively correlated with PD-L1 as well as its transcription factors IRF1 and HIF-2α." (PMID 38038129, 2023). "It was demonstrated that this impact was caused by a decreased expression of STAT1 as well as its phosphorylation, which led to a reduction in the activity of the regulator interferon regulatory factor 1 (IRF1) for PD-L1/PD-L2 in human and mouse melanoma cells." (PMID 37446908, 2023). "IRF1-induced PD-L1 expression may favor the progression of certain types of tumors, such as malignant melanoma, but basal PD-L1 levels may be sufficient to blunt host anti-tumor immunity." (PMID 33476326, 2021). "Similarly, MEK inhibition in KRAS-mutant lung cancer A549 cells and BRAF inhibition in BRAF-mutant melanoma A375 cells also increased IRF1 and IFIT1 protein levels (right)." (PMID 34535668, 2021). "Furthermore, patients with melanoma having high IRF-1 expression levels exhibit a significantly higher sensitivity towards ICI treatment than those with low IRF-1 expression." (PMID 34158547, 2021). "Moreover, Irf1, Ifitm3, and Sp100 are involved in the interferon-mediated response that plays a role in antitumor immunity in melanoma." (PMID 32831131, 2020). "As a proof of concept, combination treatment with a TLR7 agonist and MEK1/2 inhibitor synergistically extended the survival of wild-type but not Irf1-deficient melanoma-bearing mice." (PMID 31507609, 2019). "Taken together with the present results, it is highly conceivable that IL-27–induced up-regulation of TRAIL in human melanomas could be also mediated by STAT1/IRF-1 signaling." (PMID 24155891, 2013). "Moreover, the induction of IRF-1 was revealed to contribute to the IL-27–mediated inhibition of tumor growth of B16F10 melanoma." (PMID 24155891, 2013). "Furthermore, melanoma differentiation-associated gene 5, another RIG-I like receptor, has been reported to activate IRF-1, -3, and -7." (PMID 19404407, 2009). "In addition, IRF-1 expression persists after treatment selectively in melanoma metastases undergoing complete regression in response to rIL-2 therapy combined to antigen-specific immunization." (PMID 16805915, 2006). "In melanomas that were deficient in both IRF1 + IRF2, IFN treatment failed to restore the MHC I pathway and reverse the resistance to CPI, indicating that the beneficial effects of the IFN treatment were mediated through the substitutive activity of the transcription factor IRF1." (PMID 39281881, 2024). "We then examined whether IL-27 induces IRF-1 expression in these human melanomas." (PMID 24155891, 2013).
melanoma (continued). "R.E treatment enhanced pathwaysassociated with immune activation, including upregulation of ISGssuch as IRF1, MX1, and CXCL1, as well as pro-inflammatory cytokinesincluding TNF and IL6 in melanoma cells." (PMID 41341044, 2025). "In colorectal cancer and melanoma, defects in METTL3 or METTL14 promote IFN-γ-Stat1-Irf1 signaling by stabilizing STAT1 and IRF1 mRNA expression in an m6A-YTHDF2-dependent manner, thus upregulating PD-L1 expression and making tumors more sensitive to PD-L1." (PMID 38762484, 2024). "Upregulations of Cxcl9, Cxcl10, Cxcl11, Ccl5, Tap1, CD74, Irf1, Icam1, CD40, Fas and PD-L1 were detected after Mi-2β silencing and the anti-PD-1 treatment in BRafV600E/Ptennull melanomas." (PMID 38461299, 2024). "CRISRPcas9 was used to knock out IRF1 and IRF2 genes in human and mouse melanoma cells and the resulting phenotypes were analyzed in vitro and in vivo." (PMID 39281881, 2024). "SOX10 plays an important role in neural crest development and inhibits melanoma cell immunogenicity by inducing the expression of interferon regulatory factor 4 (IRF4), a negative regulator of interferon regulatory factor 1 (IRF1) transcription." (PMID 37626741, 2023). "In order to further investigate the relationship between gene expression levels of STAT1, IRF1, and FLI1 and survival probability in melanoma patients, Kaplan-Meier survival plots of high and low gene groups for these TFs were utilized." (PMID 37435067, 2023). "A total of 12 TFs were identified, among which the expression of STAT1, IRF1, and FLI1 in C4 Melanoma CORO1A was higher than that of other subtypes." (PMID 37435067, 2023). "PRELPhigh melanoma cells express increased levels of NLRC5 as well as selected IFN-γ signal transduction molecules, e.g., IRF1, IRF5, STAT1 and STAT2." (PMID 37730606, 2023). "The 12 TFs that were inferred to regulate NK and T cells activation in these modules are shown as follows: Module M1 contained the regulators IRF1, STAT1, SPI1, FLI1, IRF7, and E2F1, which are essential regulators for C4 Melanoma CORO1A." (PMID 37435067, 2023). "It has been reported to IRF1 inhibits antitumor immunity through upregulation of PD-L1 in MC38 and CT26 colon cancer and B16 melanoma mouse models." (PMID 36531216, 2022). "In agreement with mRNA changes, the IFN-γ treatment increased p-STAT1/STAT1 and IRF1 protein levels, which were abolished by adding EGCG in all three melanoma cells." (PMID 34832863, 2021). "A strong correlation between expression of RIG-I (DDX58) pathway genes (DDX58, IRF1, IRF3) and HLA-I APM genes, was also detected in melanoma biopsies from ICB-treated patients." (PMID 33554047, 2021). "De novo HLA-I APM expression is IRF1/IRF3-dependent and re-sensitizes melanoma cells to autologous cytotoxic CD8+ T cells." (PMID 33554047, 2021). "In conclusion, six hub genes (IRF1, JAK2, CD8A, IRF8, STAT5B, and SELL) were discovered to distinguish the response of melanoma patients under anti-PD-1 immunotherapy via WGCNA and integrated bioinformatics." (PMID 32316408, 2020). "The results of correlation analysis showed a significant, positive correlation (cor > 0.6, p-value < 0.05) between the expression of four hub genes (IRF1, CD8A, IRF8, and SELL) and three biomarkers in melanoma." (PMID 32316408, 2020). "Other microarray datasets studied in melanoma implicate IL-8, CXCL13, IRF1, IRF2 and IL-12 as possible prognostic markers." (PMID 24762633, 2014). "The present findings revealed that MDA-7/IL-24 treatment of melanoma cells activates phosphorylation of STAT3 and down-regulates interferon regulatory factor (IRF-1) whereas up-regulating IRF-2 expression, which reduces iNOS expression level." (PMID 22629368, 2012). "Protein complex formation between IRF-1 and DNA probes was increased in the nuclear extract of IFN-γ-treated melanoma cells (lanes 3, 4, 5 and 6)." (PMID 17319941, 2007).
melanoma (continued). "Compared with differentiated cells, dedifferentiated melanoma cell lines respond to IFN-γ with increased inflammatory signaling, which is accompanied by enhanced secretion of cytokines and increased PD-L1 levels resulting from increased IRF1 activity." (PMID 40108693, 2025). "Indeed, we identified increased IRF1 and CD274 mRNA levels after exposure of melanoma cells to IFNγ, correlating with increased membrane PD-L1." (PMID 39237877, 2024). "Importantly we found that type I and II IFN stimulation of IRF2-null melanomas restored their MHC I pathway and MHC I molecule expression and that this was in part dependent on IRF1." (PMID 39281881, 2024). "In fact, a recent study found that prior treatment with pegylated-IFN-alfa-2b increased the effectiveness of adjuvant pembrolizumab (anti-PD-1 treatment) in patients with surgically removable advanced melanoma, although IRF1 and IRF2 status was not evaluated." (PMID 39354629, 2024). "To further validate our findings in human cancers, we analyzed protein expression levels of ATXN3, PD-L1, IRF1, and HIF-2α in human lung adenocarcinoma tissue microarrays and melanoma tissue microarrays, which included 61 lung adenocarcinoma cases and 48 melanoma cases, respectively." (PMID 38038129, 2023). "More importantly, in samples from individuals with cancer (lung cancer, melanoma, breast cancer and gastric cancer), KAT8 and IRF1 condensates were also observed, and the fluorescence intensities of both proteins were positively correlated with PD-L1 expression." (PMID 36894639, 2023). "As was observed for melanoma cells, IFNγ treatment of Ptpn2 knockout CT26 and MC38 cells enhanced the expression of the IFNγ response genes Cxcl1, Ccl5, Stat1, Stat2, Stat3, Irf1, Pd-l1, Tap1, and Casp8, compared with IFNγ-treated control cells." (PMID 36968224, 2023). "Indeed, the protein expression levels of ATXN3, PD-L1, IRF1, and HIF-2α were all elevated in both lung cancer and melanoma compared with their adjacent normal tissues." (PMID 38038129, 2023). "Furthermore, we identified POU2F2, IRF1, and FOSL2 as the most highly correlated TFs with CD274 expression in melanoma across all five datasets." (PMID 34503064, 2021). "While EGCG downregulated the basal expression of IRF1 mRNA, IFN-γ upregulated its expression (9–21-fold), and this upregulation was reversed by a combination of EGCG and IFN-γ treatment in all three human melanoma cell lines." (PMID 34832863, 2021). "Moreover, IRF1 and JAK2 had been reported as biomarkers of the anti-PD-1 immunotherapy response in melanoma via clinical sample validation." (PMID 32316408, 2020). "IFN-γ then interacts with the IFN- γ receptor on melanoma cells, which activates the downstream signal cascade of the JAK/STAT/IRF1 axis, stimulates the transcription factors, IRF1 and MYC, to bind to the PD-L1 promoter, and PD-L2 requires the participation of transcription factors STAT3 and IRF1." (PMID 33256089, 2020). "Besides, in melanoma cells treated with IFN-γ, the activated IRF1 binds to the promoter of PD-L1 to regulate its PD-L1." (PMID 32628668, 2020). "Interestingly, we observed significant downregulation of the IRF transcription factor family members (IRF1, IRF2, IRF5, IRF8) corresponding to attenuated interferon signaling in TRIM28HIGH melanomas, probably as a consequence of low immune cell infiltration." (PMID 33076560, 2020). "Taken together, IRF1, JAK2, CD8A, IRF8, STAT5B, and SELL may serve as predictive therapeutic biomarkers for melanoma and could facilitate future anti-PD-1 therapy." (PMID 32316408, 2020). "Using fine needle aspirates from 25 patients who were under standard treatment for melanoma (including IFN-α), they performed gene analysis and saw that markers of an active T cell response, such as IRF1, IRF2 and TLA-1, were present in lesions that responded to treatment." (PMID 24762633, 2014).
melanoma (continued). "We previously demonstrated that IL-27 induces IRF-1 expression in mouse B16F10 melanoma cells ectopically expressing wild-type WSX-1, but not in those expressing WSX-1 mutated in the tyrosine residue critical for STAT1 binding." (PMID 24155891, 2013). "Over-expression of SOCS proteins in melanoma cell lines led to significant inhibition of Tyr701-phosphorylated STAT1 (P-STAT1) and gene expression following stimulation with IFN-α (IFIT2, OAS-1, ISG-15) or IFN-γ (IRF1)." (PMID 20398276, 2010). "Notably, treatment with IFN-γ produced higher IRF-1 mRNA levels with respect to ESTDAB-056, a melanoma cell line with normal inducibility of MHC class I antigen used as a control." (PMID 17319941, 2007). "Experiments on melanoma cell lines have also indicated significant upregulation of PD-L1 expression with the activation of several transcriptional genes, specifically JAK2, STAT1, STAT2, STAT3, IRF1 (interferon regulatory factor 1), and IRF9, in response to IFN-γ stimulation." (PMID 39690423, 2024). "Furthermore, the results suggest that a subgroup of dedifferentiated melanoma cells expresses increased levels of PD-L1, CCL2 and IL-8 in response to IFNγ, with IRF1 expression contributing highly to the upregulated inflammatory signaling responses of PD-L1high expressing cells." (PMID 39736644, 2024). "In addition to well-established IFNγ target genes such as CD274, IRF1, and B2M, three members of the PARP family—PARP9, −12 and −14—were consistently upregulated in all cell models as well as in IFNGhigh patient melanoma (comparing top 15% by IFNG expression to lowest 15% in the TCGA SKCM dataset)." (PMID 37752135, 2023). "Importantly, we discovered that STAT1, IRF1, and FLI1, the protective factors of melanoma, may regulate the response of melanoma cells to NK and T cells by modulating the expression of positive NK and T cell regulation activation-related genes." (PMID 37435067, 2023). "In addition, the protective factors of skin melanoma, STAT1, IRF1, and FLI1, may modulate melanoma cell responses to NK or T cells." (PMID 37435067, 2023). "Hence, combining with the results of survival and Cox regression analyses, it implied that the high expressions of IRF1, JAK2, CD8A, and SELL may predict a positive response to anti-PD-1 immunotherapy for melanoma patients." (PMID 32316408, 2020). "Enhanced IRF1 promoter methylation observed in TRIM28HIGH expressing melanoma patients is in line with the previous report, although further studies are needed to prove the versatility of TRIM28-mediated repression of other IRF members in “stemness high/immune low” melanomas." (PMID 33076560, 2020). "We then sought to assess whether IRF-1 is a prognostic factor in melanoma irrespective of treatment." (PMID 28331615, 2017). "In our study, DMF reversed melanoma resistance to NKmK, reducing MHC II expression without affecting upstream IFNγ targets (USF1, IRF1, IRF2)." (PMID 41078003, 2025). "Finally, the results suggested that the expression of six genes including IRF1, JAK2, CD8A, IRF8, STAT5B, and SELL had a significant ability to distinguish the responders from non-responders to anti-PD-1 therapy in melanoma with AUC > 0.6 and pAUC > 0.7." (PMID 32316408, 2020).
breast carcinoma (65 papers, 2010 to 2026). "Deletions or mutations in IRF-1 have been found in numerous human tumor tissues, including myelodysplastic syndrome, leukemia, gastric cancer and breast cancer." (PMID 35092496, 2022). "In previous studies, in vivo tumourigenicity was increased at IRF-1 deficient breast carcinoma cells." (PMID 33076322, 2020). "Loss of IRF1 expression or function has been reported to be associated with several human cancers such as breast cancer and gastric cancer." (PMID 30948928, 2019). "In fact, high IRF1 expression is significantly associated with longer survival in patients with breast cancer, specifically ER+ disease." (PMID 26460486, 2015). "Loss of the STAT1 downstream transcription factor IRF1 has been reported in MIN cases of human breast cancer." (PMID 22185785, 2011). "IRF1 was recently shown to have tumor suppressor function in breast cancer, while increased expression of IRF2 was associated with oncogenic activation." (PMID 22053985, 2011). "Members of the TGFβ family, which have long been implicated in endocrine resistance, also induce IRF1 expression that can lead to apoptosis in breast cancer cells." (PMID 22295238, 2011). "Allelic loss of IRF1 is detected in 32% of women with breast cancer (12/37 breast tissue specimens)." (PMID 22295238, 2011). "Finally, a single nucleotide polymorphism A4396G of the IRF1 gene was described in breast cancer cells." (PMID 38396830, 2024). "In addition to apoptosis, IRF-1 has been linked to the control of cellular autophagy in breast cancer." (PMID 35677632, 2022). "We found an association between rs2522057 and IRF1 expression levels in the eQTL analysis of breast cancer in this study lending support to the likelihood of involvement of the IRF1 gene in the mechanism of the SNP on breast cancer carcinogenesis." (PMID 34234117, 2021). "At the genetic level, there have been no reports of point mutations that cause IRF-1 inactivation in breast cancer; however, an IRF-1 polymorphism (A4396G) has been identified in breast cancer cell lines, and has been found to be more frequent amongst African Americans." (PMID 29599126, 2018). "Notably, a polymorphism in the IRF-1 gene was detected at a higher frequency in human breast cancer cell lines than in the general population and is more frequent in African-American than Caucasian individuals of European-ancestry." (PMID 23420765, 2013). "Loss of heterozygosity analysis at the IRF-1 locus of sporadic breast cancer demonstrated frequent loss of heterozygosity at the IRF-1 gene, which may induce low IRF-1 mRNA expression." (PMID 23420765, 2013). "CGH also implicates IRF1 loss of heterozygosity (LOH) in 50% of BRCA1 mutated breast cancer tumors." (PMID 22295238, 2011). "Moreover, the loss of heterozygosity at the IRF1 gene locus has been found to be a frequent event in human breast cancer." (PMID 22185785, 2011). "In addition, we identified IRF1, which encodes a tumor suppressor and transcriptional regulator serving as an activator of genes involved in both innate and acquired immune response, as a previously unreported breast cancer risk locus." (PMID 30988301, 2019). "Pathways identified in CXCL12 and FB2 fibroblast cell clusters from RA and in the B2 cell cluster from HER2+ breast cancer patients support that TMEM230/RNASET2/SDC2/IRF1 axis have pleiotropic functions." (PMID 40862725, 2025). "Pathways including epithelial to mesenchyme transition (EMT), apical junction, angiogenesis, and coagulation regulation were modulated with IRF1 downregulation in the HER2+ breast cancer FB2 fibroblast cell cluster." (PMID 40862725, 2025). "Another study on breast cancer cells also showed that IRF1, as part of the IFNγ and TNF-α signaling pathways, plays a role in suppressing growth and inducing apoptosis of malignant cells." (PMID 38396830, 2024). "IRF1 expression induces breast cancer cell specific growth suppression by inhibiting NF-κB activity." (PMID 38789431, 2024).